ENEMAL (enhancer lncRNA neighbor of NEAT1 and MALAT1)
Gene: Long non-coding RNA gene on chromosome 11 (65,476,202 to 65,477,572, reverse strand). Ensembl gene ENSG00000289883.
Diseases named in the same sentence as ENEMAL in open-access papers:
ENEMAL is named in the same sentence as 2 diseases in open-access papers, as found by Europe PMC text mining. Sharing a sentence is not in itself a finding about the gene and the disease. The quoted sentences say what the papers report.
breast carcinoma (1 paper, 2021). "Using RNA-seq and CAGE data, we found that eNEMAL was more highly expressed in MCF7 breast cancer cells compared to normal HMECs." (PMID 34019552, 2021). "In contrast, eNEMAL was upregulated in response to hypoxia all other cancer cell lines, demonstrating that this enhancer is hypoxic-responsive in breast cancer and its upregulation under hypoxia corresponds with that of MALAT1." (PMID 34019552, 2021). "In contrast, we observed the opposite effect with NEAT1_2 which was significantly upregulated, suggesting that eNEMAL regulates the NEAT1 isoform switch in MCF7 breast cancer cells." (PMID 34019552, 2021). "As MALAT1 and NEAT1 are consistently upregulated under hypoxia in these breast cancer cell lines, we asked if hypoxia could upregulate eNEMAL as well." (PMID 34019552, 2021). "Surprisingly, we found that eNEMAL regulates NEAT1 expression by modulating levels of the short and long isoforms in MCF7 breast cancer cells." (PMID 34019552, 2021). "This indicated that the eNEMAL is variably expressed in breast cancer subtypes and has no consistent pattern under normoxic conditions." (PMID 34019552, 2021). "We found that eNEMAL is upregulated in response to hypoxia in multiple breast cancer cell lines, but not in non-tumorigenic MCF10A cells." (PMID 34019552, 2021).
ENEMAL also shares sentences with these, for which no sentence is quoted: cancer (1 paper).